RCN3 (reticulocalbin 3)
Diseases named in the same sentence as RCN3 in open-access papers (continued):
Sharing a sentence is not in itself a finding about the gene and the disease.
tumor (8 papers, 2015 to 2025). "Comparingtumor with corresponding control samples revealed 221 differentiallyexpressed proteins (FDR < 0.05) with FTL, PCOLCE, and RCN3 beingmost striking in tumor tissue." (PMID 40574313, 2025). "Tumor sections were stained using immunohistochemistry for proliferation markers Ki67, RCN3, and CD44." (PMID 37046668, 2023). "We orthotopically implanted patient-derived control and RCN3 shRNA-transduced GSCs; survival of tumor-bearing mice was determined." (PMID 37046668, 2023). "It has been shown that RCN3 regulates the tumor cell characteristics as RCN3 promotes cell proliferation, invasion, and metastasis, and RCN3 knockdown enhances the cisplatin efficacy in ESCC." (PMID 37046668, 2023). "RCN3 is overexpressed in ESCC tissues more than in paired normal tissues and is positively associated with tumor size, lymph node metastasis, and poor outcome in patients with ESCC." (PMID 37046668, 2023). "The DEGs of fibroblasts from tumor tissues compared to adjacent normal tissues were also identified, and one of them, RCN3 is also verified by the IHC staining." (PMID 36104333, 2022). "Our results suggested the RCN3 gene plays a vital role in tumor immunity and confirmed that high RCN3 expression level was positively associated with tumor immunosuppression in multiple cancer types." (PMID 35651805, 2022). "We conducted a comprehensive analysis of RCN3, revealing its potential pro-tumor effect as well as its function of indicating patient prognosis." (PMID 35651805, 2022). "We further investigated the correlation between RCN3 expression with tumor-infiltrating immune cells and immunosuppression-related genes in pan-cancer samples." (PMID 35651805, 2022). "Herein, we applied correlation analysis between RCN3 expression and tumor immunosuppression-related genes for further validation." (PMID 35651805, 2022). "Our research highlighted the significance of RCN3 in pan-cancer and its potential oncogenic role in influencing immune infiltration and tumor immunosuppressive microenvironment." (PMID 35651805, 2022). "We first analyzed the expression characteristics of RCN3 in tumor and normal tissues from TCGA via TIMER2 database." (PMID 35651805, 2022). "The IHC staining also showed the higher expression of RCN3 in tumor tissues than in adjacent normal tissues, which confirms the upregulation of RCN3 in fibroblasts during tumorigenesis of SBA." (PMID 36104333, 2022). "Given promising in vitro results demonstrating that RCN3 knockdown reduced the proliferation and self-renewal of GSCs, we next examined whether RCN3 knockdown reduced tumor progression in vivo." (PMID 37046668, 2023). "Further, the knockdown of RCN3 improved the survival of tumor-bearing mice." (PMID 37046668, 2023). "Furthermore, we investigated the correlations between RCN3 expression and tumor immunosuppression-related genes, chemokines, and chemokines receptors." (PMID 35651805, 2022). "Our results suggested the RCN3 gene plays a vital role in tumor immunity and high RCN3 expression may indicate tumor immune inhibition status." (PMID 35651805, 2022). "Moreover, significant correlations were found between almost all tumor immunosuppression-related genes we assessed and RCN3 in COAD." (PMID 35651805, 2022). "Our results indicated that RCN3 may play a significant role in regulating tumor immunosuppressive microenvironment in pan-cancer." (PMID 35651805, 2022). "Whether RCN3 can affect tumor pathogenesis through certain common molecular mechanisms is not yet fully established." (PMID 35651805, 2022). "Furthermore, we evaluated the expression levels of RCN3 in different tumor tissues and matched normal tissues using the ggpubr package." (PMID 35651805, 2022). "Besides, Pearson chi-square tests revealed that the expression of RCN3 was significantly correlated with AJCC (P=0.012) tumor size (P=0.002) and nodal metastasis (P=0.002)." (PMID 35651805, 2022).
tumor (continued). "Importantly knockdown of RCN3 significantly enhanced the survival of tumor-bearing mice." (PMID 37046668, 2023). "Importantly, RCN3 knockdown increased the survival of tumor-bearing mice in orthotopic models." (PMID 37046668, 2023). "Thus, we comprehensively assessed molecular characteristics of RCN3 expression, genetic and epigenetic signature, prognostic value, and its potential oncogenic role in regulating immune infiltration and tumor immunosuppressive microenvironment in TCGA pan-cancer." (PMID 35651805, 2022). "Western blot results showed that FN1(11/12),LTBP1(11/12), PLOD2(11/12), RCN3(10/12), THBS1(11/12) were increased in tumor tissues (Paired-samples t-test, p < 0.05), indicating that the screening results of TMT technology were credible." (PMID 32216815, 2020). "RCN3 (r = − 0.319, p < 0.05) and CALU (r = – 0.215, p < 0.05) expressions had significantly negative correlations with tumor purity, while a weak negative correlation was observed between SDF4 expression and tumor purity (r = − 0.125, p < 0.05)." (PMID 37723418, 2023). "To further identify its prognostic roles, we derived a TAM experiment of CRC tissue and found that expression levels of RCN3 significantly correlated with the aggressive characteristics of the cancer (AJCC stage, tumor size, and nodal metastasis) as well as poor survival of patients." (PMID 35651805, 2022). "Moreover, the cell-specific expression of RCN3 was also derived using the UALCAN database and found that notheness in solid or nonsolid tumor cells, RCN3 showed a high expression in immune cells and fibroblast cells." (PMID 35651805, 2022). "High RCN3 expression indicated tumor immune inhibition status may not be conducive to immunotherapy." (PMID 35651805, 2022). "Importantly, high RCN3 expression often suggests tumor immune inhibition status, which may not be conducive to immunotherapy." (PMID 35651805, 2022). "Also, we found that expression of RCN3 was much higher in CRC tissues than in normal tissues with a higher expression level of RCN3 closely correlating to advanced American Joint Committee on Cancer (AJCC) stage, poor differentiation, increased tumor size, and poor prognosis of CRC." (PMID 35651805, 2022).
cancer (7 papers, 2016 to 2025). A tumor composed of atypical neoplastic, often pleomorphic cells that invade other tissues. "We also observed a significant positive correlation of RCN3 expression and the infiltration level of cancer-associated fibroblasts in diverse cancer types of TCGA via all or most algorithms we used." (PMID 35651805, 2022). "Based on Gene Set Enrichment Analysis, we first identified related pathways of RCN3 and its potential biological functions in pan-cancer, RCN3 was implicated in oncogenic pathways, and was related to extracellular matrix and immune regulation." (PMID 35651805, 2022). "RCN3 expression had a significant positive association with various chemokine receptors in different cancers as well." (PMID 35651805, 2022). "Overexpression of RCN3 is also associated with cancer progression." (PMID 37723418, 2023). "Consequently, RCN3 was highly expressed in most cancers and high RCN3 expression was generally associated with poor outcomes in most cancers." (PMID 35651805, 2022). "We first examined the expression difference in RCN3 in a pan-cancer scope using the UCSC XENA database." (PMID 37046668, 2023). "Lower DNA methylation levels are likely the contributed factors for the abnormal elevate of RCN3 in most cancers." (PMID 37723418, 2023). "It is essential to note that TGFB1, which is an effector of immune suppression, showed strong positive correlations with RCN3 expression levels in the vast majority of TCGA cancer types." (PMID 35651805, 2022). "Meanwhile, the expression of RCN3 was analyzed using the data of multiple types of cancers downloaded from TCGA." (PMID 35651805, 2022). "In this study, our analysis of univariate Cox proportional-hazards regression suggested the link between RCN3 expression and overall survival prognosis in 12 cancer types." (PMID 35651805, 2022). "In summary, our first pan-cancer analyses explored RCN3 expression characteristics, prognostic significance, immune cell infiltration, and associated pathways using bioinformatics methods." (PMID 35651805, 2022). "A GSVA analysis of 32 cancer types showed that expression of RCN3 significantly correlated with the pathway of epithelial mesenchymal transition (EMT)." (PMID 35651805, 2022). "Our research validated the importance of RCN3 in cancer and a comprehensive understanding of its role as a therapeutic biomarker is worth further exploration." (PMID 35651805, 2022). "We applied univariate Cox proportional-hazards regression analysis to quantify the relationship between RCN3 expression and overall survival in various cancers." (PMID 35651805, 2022). "GSEA was performed to further explore the potential biological functions of RCN3 in different cancers." (PMID 35651805, 2022). "We conducted a pan-cancer analysis to explore RCN3 expression signature, genetic alteration characteristics, DNA methylation, prognostic value, and immune regulation relevant pathways." (PMID 35651805, 2022). "Our pan-cancer analysis revealed the significant positive correlations of RCN3 expression with macrophages in most cancers from TCGA." (PMID 35651805, 2022). "Other genes whose protein products have evidence of function in cancer include RCN3, RRBP1, PDLIM3 and SLC1A4." (PMID 27689402, 2016). "Recent studies demonstrated that RCN3 expression in cancer is tissue specific." (PMID 37046668, 2023). "Thus, our pan-cancer analysis offers a deep understanding of potential oncogenic roles of RCN3 in different cancers." (PMID 35651805, 2022). "Collectively, these results indicated that RCN3 has an elevated expression in most cancers." (PMID 35651805, 2022). "Our study, for the first time, comprehensively assessed the role of RCN3 in TCGA pan-cancer." (PMID 35651805, 2022). "Therefore, both genetic alterations and lower DNA methylation levels are likely the contributed factors for the abnormal elevate of RCN3 in most cancers." (PMID 35651805, 2022).
cancer (continued). "Therefore, TIMER, EPIC, XCELL, MCPCOUNTER, TIDE, CIBERSORT, CIBERSORT-ABS, and QUANTISEQ algorithms were used to identify the potential correlation between RCN3 expression and the infiltration level of immune cells in human pan-cancer." (PMID 35651805, 2022). "The results indicated a correlation between RCN3 and oncogenic pathways, such as PI3K − Akt, pathways in cancer, and Th1 and Th2 cell differentiation." (PMID 35651805, 2022). "Moreover, we identified that RCN3 expression was positively correlated with TAMs and CAFs but negatively correlated with CD8+ T-cells in pan-cancer via TIMER2 and analyzed data from a published work." (PMID 35651805, 2022). "Additionally, there was a significant negative correlation between RCN3 expression and DNA methylation in pan-cancer." (PMID 35651805, 2022).
brain disorder (1 paper, 2023). A disease affecting the brain or part of the brain. "Challenges ahead will be to investigate the roles and function of TGM1, TGM2, ATF3, RCN3, ORAI1, and ITPR3 in TBI as well as TBI-induced secondary brain disorders." (PMID 37645012, 2023).
RCN3 also shares sentences with these, for which no sentence is quoted: rheumatoid arthritis (2 papers); systemic sclerosis (2); bladder urothelial carcinoma (1); breast invasive carcinoma (1); cardiac disease (1); cervical cancer (1); cholangiocarcinoma (1); chronic kidney disease (1); colon adenocarcinoma (1); colon cancer (1); connective tissue disease (1); endocervical adenocarcinoma (1); esophageal squamous cell carcinoma (1); fibrosis (1); gastric cancer (1); glioma (1); head and neck squamous cell carcinoma (1); idiopathic pulmonary fibrosis (1); interstitial lung disease (1); kidney chromophobe (1); kidney tumors (1); lung adenocarcinoma (1); lung squamous cell carcinoma (1); mesothelioma (1); oral cancer (1); osteosarcoma (1); ovarian carcinoma (1); ovarian serous cystadenocarcinoma (1); Pan (1); pancreatic adenocarcinoma (1).
A further 9 diseases each share a sentence with RCN3 in 1 paper.